HGF (hepatocyte growth factor)
Diseases named in the same sentence as HGF in open-access papers (continued):
Sharing a sentence is not in itself a finding about the gene and the disease.
metabolic syndrome (19 papers, 2006 to 2025). A cluster of metabolic risk factors for CARDIOVASCULAR DISEASES and TYPE 2 DIABETES MELLITUS. "Our colleagues demonstrated that HGF levels were significantly and strongly associated with metabolic syndrome." (PMID 25575766, 2015). "HGF levels correlated to age, but correction for age left the association with T2D intact (similar results were obtained with corrections for BMI and dyslipidemia)." (PMID 25500583, 2014). "A strong association has been observed between serum levels of HGF and the metabolic syndrome, although it is unclear if the molecular mechanism for this is related to the function of CD36." (PMID 16515687, 2006). "In agreement with our results, previous studies have established some associations of FGF21, HGF, and VEGF with metabolic syndrome and its various components." (PMID 38092892, 2023). "These unique character of HGF would provide us to consider new therapeutic options to treat metabolic syndrome." (PMID 28273932, 2017). "These drugs would have the potential to provide the additional beneficial properties (i.e., anti-inflammatory and anti-oxidative) through HGF production, besides their own pharmacologic targets in metabolic syndrome." (PMID 28273932, 2017). "Controlling for age, gender, dyslipidemia or liver function via hierarchical clustering showed that these factors did not contribute to the association of monocyte HGF expression with disease." (PMID 26779287, 2016). "Conversely, the upregulation of proteins such as HGF and CCL19, along with increased inflammatory cytokines like IL-6, CXCL10, and CCL8, suggests an inflammatory environment that could predispose OBO individuals to the development of a metabolic syndrome." (PMID 40076884, 2025). "The current observation of an association between plasma water T2 and HGF/MET reinforces the notion that low plasma water T2 is a biomarker of metabolic dysregulation and poor metabolic health, even in individuals without prediabetes or metabolic syndrome." (PMID 30237882, 2018).
small cell lung carcinoma (18 papers, 2007 to 2023). Small cell lung cancer (SCLC) is a highly aggressive malignant neoplasm, accounting for 10-15% of lung cancer cases, characterized byrapid growth, and early metastasis. "The MET/HGF axis appears to be another signaling pathway frequently altered in small cell lung cancer (SCLC)." (PMID 28903317, 2017). "Preclinical findings also showed that the aberrant c-MET/HGF pathway plays an important role in cytotoxic chemotherapy (CC) resistance in small-cell lung cancer (SCLC)." (PMID 29069748, 2017). "We have shown that cell motility of small cell lung cancer (SCLC) cells is increased after HGF stimulation." (PMID 17667909, 2007). "It has been demonstrated that HGF could significantly promote Small Cell Lung Cancer (SCLC) cell motility via the induction of tyrosine phosphorylation of numerous cellular proteins." (PMID 35568918, 2022). "As an example, in small cell lung cancer (SCLC), activation of MET with HGF leads to phosphorylation/activation of several pathways involving cell proliferation/survival (ERK1/2, AKT), cell cycle (RB), and cytoskeletal proteins (paxillin, FAK)." (PMID 19955662, 2009). "This is reminiscent of a previous study suggesting that ERK2, but not ERK1, mediated the HGF-induced motility of non–small cell lung carcinoma cell lines." (PMID 25607934, 2015).
Cerebral ischemia (17 papers, 2008 to 2024). Restriction of arterial blood supply to the brain associated with insufficient oxygenation to support the metabolic requirements of the tissue. "HGF protects endothelial cells against apoptosis in cerebral ischemia animal models and prevents the associated learning and memory dysfunctions." (PMID 34179015, 2021). "HGF gene-transfected MSCs are used to treat damaged endometrium, hepatocirrhosis, and ameliorate cerebral ischemia/reperfusion injury." (PMID 38213743, 2024). "HGF’s neurotrophic function, acting against cerebral ischemia in rats, reduces the infarct volume and neuronal death following AO." (PMID 39063072, 2024). "Our findings align with these previous studies, which further supports HGF as a reliable indicator of lung damage after cerebral ischemia." (PMID 35897671, 2022). "In the same hippocampal region, and after cerebral ischemia, HGF also decreases the activity of the NADPH oxidase and consequent ROS generation in glia-like cells." (PMID 34179015, 2021). "Further studies are needed to investigate how HGF affects the expression of tight junction proteins and angiogenesis after cerebral ischemia." (PMID 30151417, 2018). "Although certain obstacles remain before clinical application of HGF can be achieved, we are of the opinion that through the deepening research these issues will be overcome, bringing benefit to patients with cerebral ischemia." (PMID 25574187, 2015). "The purpose of this review is to summarize the present understanding of the therapeutic potential of HGF in cerebral ischemia." (PMID 25574187, 2015). "This suggested that HGF should be one of the most potent growth factors for treating brain ischemia." (PMID 25574187, 2015). "Increased mRNA expressions of HGF and c-met may reduce hippocampal neuronal cell death, offering potential therapeutic benefits for cerebral ischemia." (PMID 39063072, 2024). "Interestingly, HGF counteracts the oxidative DNA damage after cerebral ischemia by increasing the level of APE/Ref-1-positive cells in the hippocampal CA1 region." (PMID 34179015, 2021). "Moreover, intrastriatal injections of HGF were successful in protecting neural progenitor cells from apoptosis in animal models of cerebral ischemia." (PMID 34179015, 2021). "Overall, as a growth factor, HGF has therapeutic potential against cerebral ischemia." (PMID 25574187, 2015). "Studies in rodent models have revealed that HGF administration promotes angiogenic activity, prevents disruption of the blood–brain barrier, and promotes the survival of neurons both after cerebral ischemia and in a transgenic amyotrophic lateral sclerosis (ALS) model." (PMID 30823442, 2019). "In addition, HGF itself promotes angiogenesis after cerebral ischemia." (PMID 30151417, 2018). "MSCs engineered with HGF, via a multimutated HSC-1 vector (MSC-HGF), were used to treat brain ischemia in the superacute and acute therapeutic phases in a transient middle cerebral artery occlusion model in rats." (PMID 31720180, 2019). "Recent studies have showed that HGF could protect BBB integrity, attenuate brain edema, promote endogenous repair and functional recovery in rodent models after cerebral ischemia." (PMID 36782269, 2023). "Hepatocyte growth factor (HGF) exhibits neuroprotective effects, which may also inhibit the disruption of the blood–brain barrier after cerebral ischemia by gene administration." (PMID 35453487, 2022). "In addition, we identified and verified HGF, TGF-α, and CCL2 as dysregulated proteins in the lungs after cerebral ischemia." (PMID 35897671, 2022). "Recent studies have shown that HGF could protect blood–brain barrier (BBB) integrity, attenuate brain edema and promote endogenous repair and functional recovery in rodent models after cerebral ischemia." (PMID 36782269, 2023). "Therefore, we hypothesized that the combination of ex vivo HGF gene therapy and DPSCs would attenuate inflammatory responses and BBB disruption after cerebral ischemia." (PMID 30151417, 2018).
medulloblastoma (17 papers, 2008 to 2026). A malignant, invasive embryonal neoplasm arising from the cerebellum. "HGF/MET is a key signaling pathway in these tumors as it has been implicated in the pathogenesis of medulloblastoma." (PMID 33066121, 2020). "Our study confirms that c-MET and its ligand HGF are highly expressed in the SHH medulloblastoma subgroup, with SHH-α and SHH-β subtypes showing the highest expression levels of both genes, respectively." (PMID 41729336, 2026). "It is similarly overexpressed in pediatric medulloblastoma and ganglioglioma, where it promotes HGF-induced growth and invasiveness of medulloblastoma cells, possibly due to increased HGFR endocytosis and signaling from endosomes." (PMID 40986063, 2025). "In medulloblastoma tumor cells, Map4k4 enhances endocytic activity and the depletion of Map4k4 impairs hepatocyte growth factor-induced dextran endocytosis." (PMID 37508356, 2023). "JARID1B activates c-Met in cancer stem cells.c-Met and its ligand HGF/SF are involved in epigenetic dysregulation.SPINT2/HAI-2, an inhibitor of HGF/c-Met signaling, was silenced by promoter methylation in medulloblastoma." (PMID 34055785, 2021). "The activation of the hepatocyte growth factor (HGF) signaling is a known mechanism for the progression of medulloblastoma; its inhibition is a potential strategy for the treatment of medulloblastoma." (PMID 34975495, 2021). "Of note are the inhibition of the Wnt/β-catenin pathway, which plays an important role in one of the four medulloblastoma subgroups, and the inhibition of the Hepatocyte Growth Factor (HGF)-induced cell migration in medulloblastoma by quercetin." (PMID 26967057, 2016). "In conclusion, this manuscript describes the bypassing capacity of paracrine HGF in medulloblastoma cell lines." (PMID 26496080, 2015). "The present study demonstrates that exogenous HGF can significantly bypass the growth-inhibitory effects of canertinib in medulloblastoma cell lines." (PMID 26496080, 2015). "c-MET-Src family kinases are required for hepatocyte growth factor (HGF)/scatter factor induced TF expression in medulloblastoma cells." (PMID 25084809, 2014). "Another group demonstrated a high frequency of medulloblastomas in mice through co-overexpression of Shh and hepatocyte growth factor, HGF, the ligand for the transmembrane receptor c-Met." (PMID 20520772, 2010). "This is consistent with our previous observations that HGF induces cell cycle progression in medulloblastoma cells including the DAOY cell line." (PMID 18992144, 2008). "Earlier work by our laboratory and others has shown that human medulloblastomas frequently express HGF, c-Met and molecular constituents of the extrinsic (death receptor) apoptosis pathway." (PMID 18992144, 2008). "Human medulloblastoma cells were treated with HGF for 24–72 hours followed by death receptor ligand TRAIL (Tumor necrosis factor-related apoptosis-inducing ligand) for 24 hours." (PMID 18992144, 2008). "We reported previously that HGF protects DAOY medulloblastoma cells against chemotherapy-induced apoptosis." (PMID 18992144, 2008). "This study examines the interactions between HGF:c-Met signaling and medulloblastoma cell death/apoptosis in response to TRAIL." (PMID 18992144, 2008). "In the DAOY human medulloblastoma cell line, we found that HGF sensitizes TRAIL induced apoptotic cell death." (PMID 18992144, 2008). "We found that in a representative medulloblastoma cell line, HGF promotes TRAIL-induced medulloblastoma cell death." (PMID 18992144, 2008). "Taken together, these and previous findings indicate that HGF:c-Met pathway either promotes or inhibits medulloblastoma cell death via pathway and context specific mechanisms." (PMID 18992144, 2008). "This manuscript points to the bypassing capacity of exogenous HGF in medulloblastoma cell lines." (PMID 26496080, 2015). "HGF protein was hardly released by medulloblastoma cells itself." (PMID 26496080, 2015).
medulloblastoma (continued). "Whereas VEGF-A, PDGF-AB, FGF-2 and EGF show weak bypassing potential in addition to either crizotinib or canertinib, addition of HGF shows strong bypassing potential by significantly bypassing the growth-inhibitory effects of canertinib in medulloblastoma cells." (PMID 26496080, 2015). "HGF overexpression activated PI-3 kinase signaling; and, compared to medulloblastomas generated by overexpression of Shh alone, exogenous Shh + HGF appeared to promote tumorigenesis by inhibiting apoptosis in granule neuron precursors of the developing cerebellum." (PMID 20520772, 2010). "In this study, we show that HGF promotes medulloblastoma cell death induced by TRAIL." (PMID 18992144, 2008). "We show that HGF promotes TRAIL-induced cell death in the human medulloblastoma DAOY cell line." (PMID 18992144, 2008). "In adult patient-derived glioma cells, MAP4K4 is necessary for pro-metastatic functions, and in pediatric medulloblastoma cells, it promotes invasion induced by epidermal (EGF), hepatocyte (HGF) and basic fibroblast growth factor (bFGF)." (PMID 36568222, 2022). "Hepatocyte growth factor (HGF) and its receptor c-MET are commonly expressed in malignant gliomas and embryonic neuroectodermal tumors including medulloblastoma and appear to play an important role in the growth and dissemination of these malignancies." (PMID 18992144, 2008). "The present study investigated the role of micro-environmental growth factors expressed in the brain, such as HGF and EGF, in relation to the effects of hepatocyte growth factor receptor (MET) and epidermal growth factor receptor family (ErbB1-4) inhibition in medulloblastoma cell lines." (PMID 26496080, 2015). "Unlike in our medulloblastoma cell lines, HGF is constantly produced in vivo, suggesting potential bypass mechanisms related to the tumor micro-environment." (PMID 26496080, 2015).
uveal melanoma (17 papers, 2007 to 2025). A melanoma derived from melanocytes of the uveal tract. "cMET is a frequently overexpressed receptor tyrosine kinase in metastasis from uveal melanoma, activated by hepatocyte growth factor." (PMID 40682179, 2025). "We focused our attention on hepatocyte growth factor (HGF) since HGF production has been reported in the eye, skin, and liver, three sites where uveal melanomas can arise and/or metastasize." (PMID 37966164, 2023). "We showed that HGF, which has been reported to contribute to uveal melanoma progression and which is expressed in skin and liver, two major sites of uveal melanoma metastasis, reduced activity of the LKB1‐SIK2 module." (PMID 37966164, 2023). "Our data show that treatment of human OMM1.3 metastatic uveal melanoma cells with HGF enhanced LKB1 phosphorylation on serine 428 which has been associated with its inhibition." (PMID 37966164, 2023). "HGF induces uveal melanoma cell proliferation and survival, which produces resistance to MET inhibitors, such as crizotinib and cabozantinib, in metastatic uveal melanoma tumors." (PMID 37576814, 2023). "In uveal melanoma tumors, the PI3K/AKT and PKC/MAPK pathways are highly activated, suggesting a rationale for inhibiting these signaling cascades, and one in vitro study determined the effect of hepatocyte stimulation factor (HGF) in uveal melanoma cell lines." (PMID 37576814, 2023). "Hepatocyte stimulation factor, HGF, is present in the tumor microenvironment of uveal melanoma and recent studies have reported that a high HGF level is significantly correlated with metastatic uveal melanoma." (PMID 37576814, 2023). "Uveal melanoma cells show increased expression of a transmembrane protein called cMET, which is known as the sole receptor for the Hepatocyte growth factor (HGF)." (PMID 36761417, 2022). "Compensatory pathways are known to be activated in uveal melanoma, including HGF-c-Met, SRC, Ras, EGFR, VEGF, and phosphatidylinositol-3-kinase-AKT signaling." (PMID 32976223, 2020). "Altogether, loss- and gain-of-function studies suggest that mda-9/syntenin is involved in the activation of an invasive program mediated by HGF in uveal melanoma cells." (PMID 22267972, 2012). "In a previous study, it was demonstrated that the PI3K/Akt signaling pathway was involved in HGF-induced migration of uveal melanoma cells through the activation of c-Met." (PMID 22419847, 2012). "Hepatocyte growth factor/scatter factor (HGF), Insulin-like growth and Stem cell factor receptors have been involved in metastatic progression of uveal melanoma." (PMID 22267972, 2012). "Here, we demonstrated that miR-34b/c can inhibit uveal melanoma cell migration dramatically in an hepatocyte growth factor (HGF)-dependent fashion." (PMID 22419847, 2012). "The MG63 cell conditioned medium, which contains HGF, or recombinant HGF were used as stimulus, as HGF has been involved in uveal melanoma migration or invasion." (PMID 22267972, 2012). "A previous report indicated that HGF enhances migration of uveal melanoma cells and our present study also indicate that the HGF/c-MET axis plays a role in driving invasion." (PMID 22267972, 2012). "Hepatocyte growth factor (HGF) has been previously shown to promote the migration of uveal melanoma cell lines in vitro (SOM196B, SOM157d, SOM267, SOM269)." (PMID 17261188, 2007). "The aim of this study was to characterize the presence and roles of CXCL12, CXCL8, CXCL1, and HGF in five human uveal melanoma cell lines, using different methods, in order to ascertain their significance in this disease." (PMID 17261188, 2007). "In uveal melanoma, the epitheliod cells, (the cell type with the highest metastatic potential) were shown to express the c-met receptor for HGF." (PMID 17261188, 2007). "In conclusion, characterizing the expression of CXCL12, CXCL8, CXCL1, and HGF in uveal melanoma cell lines leads us to a better understanding of how these cytokines are integral in the metastatic process." (PMID 17261188, 2007).